ENG (endoglin)
Diseases named in the same sentence as ENG in open-access papers (continued):
Sharing a sentence is not in itself a finding about the gene and the disease.
tumor (continued). "In that tumor model, we demonstrated the anti-vascular effect of endoglin silencing, which was composed of an anti-angiogenic as well as a vascular disrupting action." (PMID 26712792, 2015). "Therapeutic effects of monoclonal antibodies targeting endoglin were already demonstrated, since endoglin expression is highly elevated during the tumor angiogenesis and vascular development, on the proliferating endothelial cells." (PMID 25909447, 2015). "Endoglin was expressed at low level in endothelial cells in normal mucosa of the rectum and strongly expressed in vascular endothelial cells in tumor vessels." (PMID 26089870, 2015). "This pattern of expression of the endoglin shows its role as proangiogenic component in tumor endothelial cells." (PMID 26089870, 2015). "This transmembrane glycoprotein is primarily expressed in proliferating endothelial cells and is upregulated by hypoxia; therefore, endoglin is strongly expressed in tumor endothelial cells." (PMID 26510973, 2015). "Endoglin has been suggested to be the most suitable marker available to quantify tumor angiogenesis." (PMID 26089870, 2015). "In order to specifically silence endoglin within tumor vasculature, plasmid with tissue specific promoter represents good option." (PMID 25909447, 2015). "In the studies using antibodies against endoglin, significant tumor growth delay and anti-metastatic action was achieved, resulting already in phase I clinical trials for the treatment of cancer with the TRC105 anti-endoglin antibody." (PMID 26712792, 2015). "Up-regulated endoglin expression has been reported during wound healing and tumor vascularization, and in inflammatory tissues and developing embryos." (PMID 25361902, 2014). "The value of immunohistochemical endoglin detection has already been demonstrated in the field of tumor diagnostics." (PMID 26034672, 2014). "CD90 (Thy-1) was strongly expressed in all EWS samples.CD105 (endoglin) was positively expressed in tumor cells and strongly expressed in the cells surrounding the tumor vessels." (PMID 24498265, 2014). "Dense staining of endoglin has been observed in the angiogenic blood vessels of more than 10 types of tumor tissues and correlated with poor prognosis, suggesting its potential as a target for clinical intervention." (PMID 24994097, 2014). "We showed human PECAM1/CD31 and ENG/CD105 expression in all tumor types, supporting existence of human tumor endothelial cells in all tumor types." (PMID 24625025, 2014). "Increased levels of antibodies to endoglin, CD31 and CD34 are associated with progression-free survival tumor grade and metastasis." (PMID 24507660, 2014). "The overexpression of endoglin in proliferating vascular endothelial cells during tumor angiogenesis and vascular development makes endoglin targeting a promising antiangiogenic therapeutic approach in cancer treatment." (PMID 23593103, 2013). "Due to the increased expression of endoglin in angiogenic endothelium, antibodies targeting endoglin have already been used for tumor imaging and endoglin was proposed to be used as prognostic tumor marker." (PMID 23593103, 2013). "ENG is mainly expressed in proliferating vascular endothelium and its expression increases during tumour angiogenesis and inflammation." (PMID 23341958, 2013). "Three repetitive intratumoral injections of m_siRNA 869 only also had a minor effect on tumor growth and on endoglin mRNA level, which was reduced for ∼60%, but the difference was not statistically significant." (PMID 23593103, 2013). "Elevated expression of ENG correlates with the proliferation of tumour endothelial cells and also in hematopoietic tumours such as multiple myeloma and in hairy cell leukemia." (PMID 23341958, 2013). "Endoglin (ENG) is an integral membrane glycoprotein whose properties have made it a reliable marker of tumour angiogenesis and a prime target for anti-angiogenic therapy." (PMID 23341958, 2013).
tumor (continued). "On the other hand, a triple electrotransfer of m_siRNA 869 reduced the endoglin mRNA level for up to 80% which resulted in a pronounced antitumor effect and significantly delayed tumor growth." (PMID 23593103, 2013). "When repetitive treatments with toxin-conjugated or radiolabelled anti-endoglin antibodies were performed, a long-lasting regression of tumor growth was obtained, whereas naked antibodies had less pronounced effect on tumor growth." (PMID 23593103, 2013). "As ENG staining represents a powerful marker to quantify tumor angiogenesis we have evaluated the expression of ENG in MDS cells and we have demonstrated an over-expression in the high-risk cases." (PMID 23341958, 2013). "Expression of endoglin in endothelial cells, tumor cells and tumors, expressed as threshold cycle values (Ct) obtained by qRT-PCR in comparison to reference gene." (PMID 23593103, 2013). "Endoglin has been also suggested as an appropriate marker for tumor-related angiogenesis and neovascularization and numerous studies demonstrate the potential of endoglin in tumor diagnosis, prognosis and therapy." (PMID 22929622, 2012). "Although the exact mechanism by which endoglin induces tumor angiogenesis remains to be illustrated, it is well accepted that endoglin acts as a positive regulator of ALK1 signaling and a negative regulator of ALK5 signaling in endothelial cells." (PMID 23209720, 2012). "Our results indicate that toxicarioside A suppresses tumor growth through inhibition of endoglin-related tumor angiogenesis, which involves in the endoglin/TGF-β signal pathway." (PMID 23209720, 2012). "Diffuse staining of a subset of microvessels in tumour-adjacent mucosa of the oesophagus by CD105/endoglin, a neovascularisation marker, has been found to correlate statistically with worse overall survival of the patients." (PMID 22472880, 2012). "Sections of tumor tissue were stained using monoclonal endoglin antibody and a FITC-conjugated second antibody." (PMID 23209720, 2012). "Immunotherapies with anti-endoglin monoclonal antibody, DNA and protein vaccines against endoglin have been shown to inhibit tumor growth and metastasis by suppressing endoglin-related angiogenesis in vivo." (PMID 23209720, 2012). "Our results indicate that toxicarioside A can suppress tumor growth by inhibiting angiogenesis, which involves in the endoglin/TGF-β signal pathway." (PMID 23209720, 2012). "Smad1 but not Smad2/3 protein levels were significantly decreased, suggesting that endoglin plays a role in the attenuation of endothelial tumor growth and tumor angiogenesis." (PMID 23209720, 2012). "There was a trend close to significance for a shorter metastasis-free survival in patients with high endoglin expression in more than 50% of the tumor cells (p=0.052)." (PMID 23088614, 2012). "Northern and Western blot analysis showed significant inhibition of endoglin expression in toxicarioside A-treated human umbilical vein endothelial cells (HUVECs) in vitro and tumor tissues in vivo." (PMID 23209720, 2012). "Recently, it has been shown that TRC105, a chimeric IgG1 monoclonal antibody binding to endoglin, inhibits tumor angiogenesis and appears to have a safety profile in a clinical phase I trial." (PMID 22929622, 2012). "Compared to Flt1, endoglin is possibly a more specific target for cancer therapy, since its expression is more tumor-related." (PMID 22929622, 2012). "Deletion of CD4(+) T-lymphocytes abrogated the anti-tumor activity and endoglin-specific autoantibodies." (PMID 21385454, 2011). "Nigrin b and ebulin l have been used to also construct immunotoxins containing anti-human endoglin to target tumor neovasculature which nourishes tumor cells." (PMID 22069717, 2011). "Given that TGF‐β signaling activation is mediated by ENG expression in CAFs, we reasoned that ENG expression might be involved in the tumor‐promoting ability in these cells." (PMID 40644310, 2025).
tumor (continued). "Although VEGF expression correlates with increased tumor vascularization, recent evidence suggests that other angiogenic regulators, notably endoglin, may play even more significant roles in metastasis and tumor aggressiveness." (PMID 40647381, 2025). "For example, targeting endoglin, a protein involved in vascular remodeling and angiogenesis, promoted tumor blood vessel normalization, increased T lymphocyte and NK cell infiltration and repolarized TAMs to an anti-tumor state in melanoma." (PMID 39567756, 2025). "Consequently, ablation or inhibition of endoglin reduces angiogenesis and tumor growth in cancer mouse models." (PMID 40650130, 2025). "Given the significantly attenuated TGFB1 expression levels in exp‐CAF2‐shENG cells, we speculated that the decreased TGF‐β1 production contributed to the suppression of primary tumor growth and metastasis by ENG reduction in CAFs." (PMID 40644310, 2025). "In a study of mice injected with Lewis lung carcinoma (LLC), continuous overexpression of endoglin was shown to impair the integrity and maturity of tumor vascularization, leading to leaky vessel walls that facilitate intravasation of tumor cells into the bloodstream." (PMID 38761292, 2024). "The authors suggest that endoglin concentration in tissue may correlate with the degree of tumor malignancy." (PMID 39684268, 2024). "Additionally, in vitro immune-mediated cytotoxicity assays showed that T cells induced specific lysis of cells expressing endoglin, thus confirming the efficacy and specificity of induced anti-tumor response." (PMID 39081320, 2024). "Additionally, ENG expression levels were positively correlated with MerTK in the TCGA primary TNBC tumor samples." (PMID 38791148, 2024). "When stratifying EC patients based on tumor size, five proteins were significantly increased in patients with tumors larger than 2 cm: endoglin (p = 0.03), FAP (p = 0.001), HB-EGF (p = 0.04), MIA (p = 0.01), and VEGF-A (p = 0.02), when compared to patients with smaller tumors (≤ 2 cm)." (PMID 39511039, 2024). "We assumed that ENG might be a novel target for tumor immune response and immunotherapy in pancancer including BRCA and TNBC." (PMID 39247590, 2024). "Additionally, siRNAs designed to downregulate endoglin expression have been investigated primarily in the context of cancer, particularly for their role in inhibiting tumor angiogenesis, a critical process for tumor growth and metastasis." (PMID 38994958, 2024). "ENG has been identified as a tumor-suppressor gene in many cancers, including ESCC." (PMID 39247590, 2024). "Moreover, tumor-associated angiogenesis is induced by angiogenic factors, including VEGF and ENG, which are upregulated under hypoxic conditions." (PMID 38242992, 2024). "TGFβ is a co-receptor of ENG and essential for angiogenesis as well as tumor vascularization." (PMID 38791148, 2024). "Tumor behavior can be directly influenced by the processes in which endoglin is involved." (PMID 39552710, 2024). "In addition, analysis of 115 primary TNBC tumor samples from TCGA showed a positive correlation (Spearman’s rank correlation coefficient = 0.234, p-value = 0.012) between ENG and MerTK RNA levels." (PMID 38791148, 2024). "There is still debate as to the role of ENG as a tumor promoter or a tumor suppressor, with data suggesting that it may depend on the cancer cell type." (PMID 38791148, 2024). "Our data suggest a role for ENG as a tumor promoter in TNBC." (PMID 38791148, 2024). "One study used IF to label tumour-derived endothelial cells that had undergone tube formation and showed that they expressed CD105 (endoglin), a cell surface glycoprotein normally expressed by vascular endothelial cells that is associated with endothelial proliferation and angiogenesis." (PMID 36823554, 2023). "Endoglin expression was evaluated in tumor specimens and 14 patient-derived cell lines." (PMID 37396898, 2023). "Specific expression of endoglin on epithelial tumor cells was evaluated." (PMID 37396898, 2023).
tumor (continued). "Firstly, we analyzed tumor cell specific endoglin expression in these tumors using patient samples." (PMID 37396898, 2023). "Furthermore, levels of endoglin/CD105 have been shown to positively correlate with the extent of endothelial cell proliferation and with the expression of proliferation markers in tumour endothelia." (PMID 37052868, 2023). "Endoglin expression in patient biopsies could be an excellent biomarker of the immunosuppressive tumour microenvironment and may predict patients’ response to immunotherapy [23•]." (PMID 37052868, 2023). "On CAFs, endoglin has been shown to promote tumor progression and metastasis." (PMID 37396898, 2023). "Interestingly, when we analyzed ESCC, HNSCC, and VSCC patient samples we observed that endoglin expression was restricted to individual cells in the tumor nest." (PMID 37396898, 2023). "The results of this study showed a high level of endoglin expression in tumor samples." (PMID 36844233, 2023). "In conventional VSCC, we found once again both tumor cells and macrophages expressing endoglin." (PMID 37396898, 2023). "Endoglin might be a useful marker for tumor angiogenesis detection in studies testing novel targeted therapy in combination with chemotherapy and VEGF inhibitors as well as a single agent." (PMID 34587660, 2022). "Moreover, inhibin secreted by tumor cells induces angiogenesis via SMAD1/5 signaling in endothelial cells in a paracrine manner dependent on the type III TGFβ receptor endoglin/CD105 and the type I TGFβ receptor ALK119." (PMID 35654828, 2022). "However, it seems that the prediction probability of endoglin highly depends on tumor biology and other factors." (PMID 34587660, 2022). "Contrary to what was postulated, endoglin overexpression does not cause an increase in tumor vascularization that expedites the intravasation and metastasis of tumor cells." (PMID 35409247, 2022). "Interestingly, the shINHA tumor cells produced more activin and endoglin compared to shControl tumors." (PMID 35654828, 2022). "CD105, also known as endoglin, is a disulfide-linked homodimeric hypoxia-inducible cell membrane glycoprotein of 180 kDa, which acts as a co-receptor for TGF-β and is highly expressed in ECs with active tumor proliferation." (PMID 36185269, 2022). "Indeed, ENG is highly expressed by neovessels within the tumor in most cancer types, with very few showing expression in the tumoral compartment." (PMID 35955799, 2022). "Although the efficacy of endoglin-based whole-tumor imaging could be questioned due to the proclivity of endoglin expression on activated endothelium rather than on malignant cells, similar tracers and novel insights suggest differently." (PMID 33946583, 2021). "Moreover, this ENG inhibition sensitizes tumor cells to gemcitabine, a conventional chemotherapeutic drug." (PMID 33804796, 2021). "Considering the great achievements of anti-angiogenesis therapy in VS and the specificity of CD105 to indicate the vascular front where sprouting takes place, it seems reasonable to use circulating CD105 to monitor tumor growth and to treat VS with anti-endoglin antibodies." (PMID 34646772, 2021). "In the MSC context, endoglin is involved in MSC migration to the tumor site." (PMID 34579743, 2021). "However, inhibiting VEGF and endoglin reduces tumor angiogenesis and decreases metastatic spread on BC cells." (PMID 35010954, 2021). "Below, we firstly summarize the recent evidence suggesting that ENG acts as a tumor promoter followed by data supporting that ENG might play a tumor suppressive role in some cancer types." (PMID 33804796, 2021). "Therefore, those carcinomas would be good candidates for endoglin-based imaging, even when endoglin’s tumor promoting or suppressing role in these settings remains currently undetermined." (PMID 33946583, 2021). "Tumor endothelial cells express endoglin, and endoglin is upregulated in HCC stem cells." (PMID 33809908, 2021).
tumor (continued). "There are a growing number of clinical trials testing the combination of the TRC105 anti-human ENG antibody with standard therapies in different tumor types, including chemotherapeutic agents (paclitaxel or carboplatin) or VEGF inhibitors (bevacizumab, sorafenib, or pazopanib)." (PMID 33804796, 2021). "Furthermore, co-administration of recombinant human endoglin partially yet significantly reduced tumor growth." (PMID 33995664, 2021). "Evidence suggests an anti-angiogenic function for Sol-ENG in cancer and, indeed, the ENG extracellular domain fused to an immunoglobulin Fc domain (ENG-Fc) that mimics Sol-ENG reduces in vitro and in vivo angiogenesis and inhibits tumor growth in a xenograft model of CRC." (PMID 33804796, 2021). "Herein, we showed that the bispecific hEND-CD3/BiTE antibody we developed specifically targeted endoglin+ cells, including those ectopically expressing endoglin (293T-hE) and normal, as well as tumor endothelial cells expressing endogenous endoglin (HUVEC and Td-EC)." (PMID 33995664, 2021). "Therefore, endoglin is a key protein in tumor growth and survival, cancer cell metastasis, and liver fibrosis." (PMID 33809908, 2021). "However, the lack of stability and maturation of the vessels produced by the endoglin overexpression increases the presence of intratumor hemorrhages and the number of circulating tumor cells and pulmonary metastases." (PMID 33800564, 2021). "Regulation of extravasation by endoglin may also account for lower IL-6 and IL-10 expression and M2 macrophage infiltration seven days after tumor implantation in tumors from Eng-iKOe mice." (PMID 33800564, 2021). "Endoglin protein levels were similar in tumor stroma and endothelium and correlated within tumors." (PMID 33471197, 2021). "This lack of ENG expression was associated with a more invasive phenotype, supporting the role of ENG as a cell invasion- and tumor-suppressor gene in these cancer types." (PMID 33804796, 2021). "Hence, in the in vivo situation, only the stromal fibroblasts which express murine FAP and the tumor endothelial cells which express the murine endoglin should take up and activate the liposomes." (PMID 32316521, 2020). "Moreover, endoglin expression in tumor cells was positively correlated with E-cadherin, β-catenin, and Syndecan-1." (PMID 33276489, 2020). "Thus, we elucidated the potential of bispecific liposomes targeting the fibroblast activation protein (FAP) on tumor stromal fibroblasts, together with endoglin which is overexpressed on tumor neovascular cells and some neoplastic cells." (PMID 32316521, 2020). "Next to regulatory T-cells, endoglin is highly expressed on some tumor cells directly targeting endoglin-expressing tumor cells, which might induce a direct anti-tumor response." (PMID 32059544, 2020). "This suggests that endoglin expression by TAFs may be negligible in our models, or is tumor type specific, similar to the expression of endoglin on a selected number of neoplastic cells." (PMID 32316521, 2020). "Moreover, enhanced endoglin expression in tumor microvessels is a better outcome predictor for some cancer types than the levels of other angiogenesis-related molecules." (PMID 31897911, 2020). "The two forms of Endoglin, membrane and soluble, can also be used to monitor the tumor samples." (PMID 32434528, 2020). "Interestingly, an antibody against endoglin (TRC105/Carotuximab) significantly decreased their number within a mouse MC38 tumor." (PMID 32059544, 2020). "Our first hypothesis was that endoglin overexpression will result in increased tumor vascularization and growth." (PMID 31897911, 2020). "In agreement with the previous results, compared with WT lungs, ENG+ lungs had more tumor foci." (PMID 31897911, 2020). "One limitation of our study is that endoglin overexpression also occurs in all cell types other than ECs, including those in the tumor microenvironment, which may also play an important role in the malignancy of tumors." (PMID 31897911, 2020).